DMC1 (DNA meiotic recombinase 1)
Description:
Homologous DNA recombinase that catalyzes strand exchange during meiotic recombination. Specifically required for meiotic recombination, facilitating the search and repair of DNA using the homolog rather than the sister chromatid, and can tolerate mismatches in heteroduplex DNA, unlike the higher-fidelity RAD51.
Synonyms: DMC1H; LIM15; dJ199H16.1
Tractability: Small molecule: a structure with a bound ligand is known; it has a high-quality binding pocket.
Gene: Protein-coding gene on chromosome 22 (38,518,905 to 38,570,211, reverse strand). Ensembl gene ENSG00000100206.
Subcellular location: Chromosome; Nucleus
Subcellular location (Human Protein Atlas): Nucleoplasm
Pathways (Reactome):
Reproduction: Meiotic recombination
Gene Ontology:
Molecular function: ATP-dependent activity, acting on DNA; DNA strand exchange activity; identical protein binding; protein binding; single-stranded DNA binding; ATP binding; DNA binding; double-stranded DNA binding; ATP-dependent DNA damage sensor activity; catalytic activity, acting on DNA; nucleotide binding
Biological process: double-strand break repair involved in meiotic recombination; homologous chromosome pairing at meiosis; reciprocal meiotic recombination; DNA recombinase assembly; DNA strand invasion; female gamete generation; female meiosis I; male meiosis I; meiotic cell cycle; mitotic recombination; spermatogenesis; DNA metabolic process; DNA repair; double-strand break repair via homologous recombination
Cellular component: chromosome; nucleus; condensed nuclear chromosome; nucleoplasm; chromosome, telomeric region; lateral element; site of double-strand break
Genetic constraint (gnomAD): Loss-of-function variants: 19 observed, 28.16 expected, observed/expected ratio (o/e) 0.67, 90% interval 0.47 to 0.99. The upper end of that interval is the gene's LOEUF score, 0.99, which puts it in group 4 of 6, group 1 being the genes least tolerant of losing a copy. Missense variants: 206 observed, 316.82 expected, observed/expected ratio (o/e) 0.65, 90% interval 0.58 to 0.73. Synonymous variants: 114 observed, 105.64 expected, observed/expected ratio (o/e) 1.08, 90% interval 0.93 to 1.26.
Homologues: Orthologues: chimpanzee DMC1 (100% identical), dog DMC1 (99% identical), pig DMC1 (99% identical), rabbit DMC1 (98% identical), guinea pig DMC1 (98% identical), rat Dmc1 (97% identical), mouse Dmc1 (97% identical), tropical clawed frog dmc1 (92% identical), zebrafish dmc1 (89% identical). Paralogues in human: RAD51 (54% identical), RAD51C (27% identical), RAD51B (23% identical), XRCC3 (21% identical), RAD51D (20% identical), XRCC2 (15% identical).